ENSG00000252692
Synonyms: LOC124900428
Gene: Small nucleolar RNA gene on chromosome 1 (206,080,239 to 206,080,324, forward strand). Ensembl gene ENSG00000252692.
Gene Ontology:
Biological process: RNA processing
Cellular component: nucleolus
Homologues: Paralogues in human: SNORD60 (72% identical).